IL2 (interleukin 2)
Diseases named in the same sentence as IL2 in open-access papers (continued):
Sharing a sentence is not in itself a finding about the gene and the disease.
COVID-19 (continued). "In addition, CD8 + T cell degranulation was reduced in COVID-19 patients compared with healthy donors, resulting in reduced production of IL-2, IFN-γ, and granzyme B." (PMID 35305698, 2022). "It has been suggested that administration of IL-2 may be an effective therapy by increasing lymphocyte numbers in COVID-19 patients." (PMID 35782361, 2022). "In our study, we detected a significant increase in IL-2 production by PBMCs but not by neutrophils, which may indicate that PBMCs play a role in the elevated serum IL-2 levels in ICU patients with COVID-19." (PMID 36363785, 2022). "In our COVID-19 cohort, we observed increased levels of IL-2, IL-4, IL-15, IL17, and IP-10, which likely activate both T-helper-1 (Th1) and T-helper-2 (Th2) cells and lead to lung inflammation and damage, similar to what has been reported in SARS-CoV and MERS-CoV infections." (PMID 36423162, 2022). "Also, IL-2-secreting T-cell responses in COVID-19 convalescents after the first dose were comparable to those after the second dose (median: 370.5 vs 363.5, P = 0.54)." (PMID 36283534, 2022). "Furthermore, COVID-19 vaccines induce T cell responses which can be evaluated by IFNγ release, IL-2 release, or both." (PMID 36105809, 2022). "In COVID-19, cytokine storms are triggered by the action of IFNγ, TNFα, IL-1, IL-2, and IL-6." (PMID 34436742, 2022). "Besides IL-6, patients with severe cases of COVID-19 have higher plasma levels of other elements of cytokine storms, including IL-2, IL-7, IL-8, IL-10, and tumor necrosis factor-α (TNF-α)." (PMID 35295802, 2022). "Recent studies on COVID-19 suggest that cytokine release syndrome is associated with the severity of disease; this syndrome is characterized by increased TNF-α, interleukin (IL)-6, IL-2, IL-7, and IL-10." (PMID 36361745, 2022). "COVID-19 symptoms rapidly become critical 7–10 days after onset, which is associated with an increase in acute-phase response markers, including CRP and ferritin, and inflammatory cytokines, including IL-6, IL-2, and TNF-α." (PMID 34436742, 2022). "As IL-2 contributes to the development of both Tregs and Th17 cells, treatment with low concentrations of IL-2 might resolve the Treg/Th17 imbalance in COVID-19 patients." (PMID 35874688, 2022). "Moreover, severe COVID-19 patients requiring intensive care in the hospital have high plasma IL-2, IL-7, IL-10, and TNF-α levels." (PMID 36035409, 2022). "Moreover, we discuss the currently available data regarding the mechanism of action of immune checkpoint inhibitors and IL-2 analogs in the treatment of COVID-19." (PMID 35852114, 2022). "Nevertheless, this case gave us the opportunity to discuss the possible mechanisms of action of ICIs and IL-2 analogs in COVID-19 and we believe that it may alert clinicians to collect similar data and possibly clarify the issues raised." (PMID 35852114, 2022). "IL-2 is majorly produced by CD4+ and CD8+ T cells, as well as some B cells and dendritic cells; its important function is to foster the proliferation of CD4+ and CD8+ T cells Few recent studies have reported that higher levels of IL-2 was seen in asymptomatic and mild COVID-19 groups." (PMID 35336918, 2022). "Furthermore, we observed that the major transcript of multiple genes switched to a different transcript (isoform switching) between COVID-19 patients and controls, such as IL2, IL34, SERPINE2, NCBP1, HRAS, PRPF6, NCBP2, and LUC7L2." (PMID 35421082, 2022). "The significant increase in IL-2 and IL-5 production by PBMCs may indicate the involvement of PBMCs in the increased IL-2 and IL-5 levels observed during the cytokine storm in COVID-19 ICU patients." (PMID 36363785, 2022). "Upon in vitro stimulation with anti-CD3/CD28 antibodies, CD4 T cells of COVID-19 patients showed a lower capacity to express IFNγ and IL-2 and proliferated together with the number of CFSElow cells (a measure of T-cell proliferation) compared to similar T-cell subsets of the control group." (PMID 35632823, 2022).
COVID-19 (continued). "Additionally, a phase 3 clinical trial has been registered recently for cytokines therapy on COVID-19 patients, evaluating the efficacy and safety of treatment with IL-2 or inhibitor of IL-17 (ClinicalTrials.gov Identifier: NCT04724629)." (PMID 35874688, 2022). "Particularly, IFN-γ and IL-2 production, mostly known to characterize a Th1 profile, were associated with a better outcome for SARS-CoV-2 infected patients and their increase was seen after the two-dose regimen of several approved COVID-19 vaccines." (PMID 36341425, 2022). "Assessment of cytokine levels among patients with acute COVID-19 and individuals in the post-COVID-19 period showed significantly higher levels of IL-17 (p=0.0002), TNF-α (p<0.0001) and IL-2 (p<0.0001) in the post-COVID-19 group and higher levels of IL-6 (p<0.0001) in the acute COVID-19 group." (PMID 35846757, 2022). "In the severe form of COVID-19, the concentrations of IL-2, IL-6, IL-10, and IFN-γ were elevated." (PMID 35782361, 2022). "Accordingly, we evaluated the levels of IL-17, IFN-γ, TNF-α, IL-10, IL-6, IL-4 and IL-2 in patients with clinical COVID-19 and long COVID-19, with cases classified as mild, moderate and severe, and associations with risk factors for sex, age and presence of comorbidities." (PMID 35846757, 2022). "Next, patients with acute COVID-19 had elevated numbers of peripheral blood CD4+ T cells simultaneously producing IL-2 and IL-17 than healthy controls in response to in vitro stimulation with anti-CD3/CD28, pointing to effector Th skewing toward the Th17 phenotype." (PMID 36146622, 2022). "COVID-19 respiratory distress begins with an early inflammation so that pulmonary compliance is reduced by activation of intercellular inflammatory pathways, cytokine synthesis, or storm (excessive release of IL-2, IL-6, IL-7, IL-8, IL10, and TNF-α)." (PMID 35656183, 2022). "Immune cell profiling analysis predicted that IL-2 may be beneficial for the recovery of COVID-19 patients." (PMID 35852114, 2022). "Furthermore, high serum levels of IL-17 and IL-2 and low levels of IL-4 and IL-10 appear to constitute a cytokine profile of long COVID-19, and these markers are potential targets for COVID-19 treatment and prevention strategies." (PMID 35846757, 2022). "However, succumbed patients generally showed lower levels of IL-1 β, IL-2, and IL-8 than the levels in patients who survived COVID-19." (PMID 36294868, 2022). "This cell-host interaction is important as many of the cytokines produced in response to COVID-19 (i.e., interleukin-1 beta (IL-1β), IL-2, IL-6, IL-8, IL-10, and tumor necrosis factor alpha (TNFα)) stimulate infiltration of macrophages, monocytes, and neutrophils into the lung tissue." (PMID 35033181, 2022). "Moreover, current COVID-19 vaccines are known to induce a strong poly-specific T-cell response mediated by IFN+ or IL-2+ CD8+ and CD4+ Th1-cells." (PMID 35990701, 2022). "Furthermore, COVID-19 convalescent individuals showed accompanying antigen peptide pools stimulated-IL-2 response, -IFN-γ response, and -IL-5 response." (PMID 34234102, 2021). "Based on our results and these previous studies, we speculate that IL-2, IL-4, and INF-γ are involved in the infiltration of alveolar inflammatory cells and lung injury caused by COVID-19." (PMID 33967617, 2021). "This dysfunction in the IL-2/CD122 axis may have prognostic implications as indicated by a recent study that suggested that reduced IL-2 levels is a warning factor for disease progression in COVID-19 patients." (PMID 34682920, 2021). "The interrelationship of immune cells in COVID-19 was intrinsically identified, whereby T cells secreting IL-2, IL-4, and IL-17A were enriched among CD28+ and CD57− cells and cells secreting perforin/granzyme B/IFN-γ/tumor necrosis factor alpha (TNF-α)-expressed markers of terminal differentiation." (PMID 34488453, 2021).
COVID-19 (continued). "NDG from severe/critical COVID-19 patients may be primed in vivo to spontaneously produce NETs, since they are exposed to IL-6, IL-2, IL-7, TNF, CXCL10, MCP-1, MIP1a, GM-CSF and M-CSF during the cytokine storm." (PMID 34685525, 2021). "Based on the presented results, we singled out IL-2/INFγ ratio as the strongest marker for a critical course of COVID-19 among hospitalized patients with SARS-CoV-2 infection, with the area under the ROC curve (AUC) being 0.859 (95%CI:0.780–0.939), and with 73.5% specificity and 90% sensitivity." (PMID 34071149, 2021). "The concentrations of IL-1, IL-2, and IL-17 were reported in only four COVID-19 studies." (PMID 34046036, 2021). "However, in contrast to previous studies, our data show that the concentration of IL-2 in COVID-19 patients is significantly lower than that in healthy individuals." (PMID 34489974, 2021). "Analysis of plasma from patients with COVID-19 has revealed increases in cytokines, including IL-1β, IL-2, IL-6, IL-7, IL-10, TNFα, monocyte chemoattractant protein (MCP1/CCL2), granulocyte colony stimulating factor (G-CSF), and macrophage inflammatory protein 1α (MIP1α/CCL3)." (PMID 34251989, 2021). "The increased expression of NKG2A in COVID-19 patients was associated with a decreased secretion of IFN-γ, IL-2, and granzyme B from both NK and CD8 T cells, suggesting that the impaired immune response during SARS-CoV-2 is due at least in part to exhausted NK and CD8 T cells." (PMID 33613573, 2021). "A recent study demonstrated that the concentration of sIL-2R in the blood may be a co-indicator of the severity of COVID-19 with lymphopenia, through IL-2 signaling inhibition." (PMID 34575353, 2021). "Severe COVID-19 cases also revealed higher levels of IL-2, IL-6, IL-10, and TNFα." (PMID 33869282, 2021). "Some hypotheses concerning low Treg levels in COVID-19 patients suggested that low IL-2 parallel with high IL-6 in severe cases leads to enhanced apoptosis of Treg cells." (PMID 34071149, 2021). "In addition, critically ill COVID-19 patients had significantly higher levels of IL-2, IL-4, and INF-γ than those with moderate or severe disease 33, 34, and those with severe COVID-19 had higher levels of certain cytokines than those with mild disease." (PMID 33967617, 2021). "In addition, our immunofluorescent staining also showed co-localization of IL-2 with IL-6 was primarily in maternal blood in COVID-19 placentas." (PMID 35071136, 2021). "Severely ill patients hospitalised with COVID-19 exhibit increased levels of many cytokines, including Interleukin (IL)-1β, IL-2, IL-6, IL-7, IL-8, IL-10, IL-17, granulocyte colony stimulating factor (G-CSF), monocyte chemoattractant protein 1 (MCP-1) and tumor necrosis factor (TNF)." (PMID 34205262, 2021). "Ld-IL2 therapy was registered for clinical trials on COVID-19 patients (ClinicalTrials." (PMID 34618873, 2021). "In COVID-19, serum concentrations of proinflammatory cytokines, including IL-2, IL-6, and tumor necrosis factor (TNF)-a, were markedly increased in severe cases than moderate cases, suggesting that cytokine storms could be associated with disease severity." (PMID 34903765, 2021). "The presence of IL-2 in COVID-19 patients indicate activation of the adaptive immune response." (PMID 34305892, 2021). "Patients with COVID-19 have elevated levels of various cytokines such as IL-2, IL-4, IL-6, and IL-10, TNF-α, IFN-γ and may present with the so-called cytokine storm." (PMID 34684384, 2021). "Even though inflammatory cytokine storms were thought to be a mechanism for COVID-19 progression, there was only an increase in IL-2, IL-4, IL-6, IL-10, TNF-α, and IFN-γ when comparing pneumonia patients with healthy people, but no significant increase in severe patients compared to mild patients." (PMID 32985562, 2020).
COVID-19 (continued). "The cytokine storm landscape of COVID-19 patients was further demonstrated in a retrospective study showing higher concentrations of IL-2, IL-7, IL-10, G-CSF, C-X-C motif chemokine ligand (CXCL)-10, C-C motif chemokine ligand (CCL)-2, CCL-3, and TNF-α in the plasma of severe COVID-19 patients." (PMID 33584335, 2020). "Our data suggested the importance of IL-2 signaling in lymphopenia of COVID-19 patients." (PMID 32587367, 2020). "A previous study found that intensive care unit (ICU) patients with COVID-19 had higher plasma levels of interleukin (IL)-10, IL-2, IL-7, tumor necrosis factor (TNF)-α, IP-10, monocyte chemoattractant protein 1, Macrophage inflammatory protein 1A than those in non-ICU patients with COVID-19." (PMID 32727465, 2020). "Our results also indicate the potential protective function of IL-2 signaling, which may delay the onset of lymphopenia for COVID-19 patients." (PMID 32587367, 2020). "Moreover IL-1β, IL-2, IL-5, IL-18, TNFα, and GM-CSF became detectable in all the samples following co-culture between resting PBMCs from COVID-19 patients and DPSCs." (PMID 33634100, 2020). "In COVID-19, this cytokine storm is characterised by the increase of interleukin (IL)-2, IL-7, granulocyte-colony stimulating factor, IFN-γ, inducible protein (IP)-10, monocyte chemoattractant protein (MCP)-1, macrophage inflammatory protein (MIP) 1-α, and tumour necrosis factor (TNF)-α." (PMID 33101440, 2020). "Cytokine storm was observed in severe COVID-19 patients with high levels of various serum cytokines, such as IL-2, IL-7, IL-10, TNF-α, granulocyte-colony stimulating factor (G-CSF), interferon gamma-induced protein 10 (IP-10; CXCL10), and monocyte chemotactic protein-1 (MCP-1)." (PMID 33251234, 2020). "Combined with the important function of IL-2 signaling in T cells, we speculated the important function of sIL-2R during the onset of lymphopenia in COVID-19 patients." (PMID 32587367, 2020). "Importantly, IL2RA expression was significantly increased in severe COVID-19 patients in comparison to moderate patients, whilst very few T-cells expressed IL2." (PMID 33178221, 2020). "The lymphopenia observed in COVID-19 may, in part, arise as a result of IL-2 signaling inhibition due to the increased soluble IL-2 receptor seen in ours and other cohorts." (PMID 32957548, 2020). "Therefore, the replacement cytokine-based therapy, with IL-2 stimulating lymphocyte proliferative activity, seems particularly appropriate in patients with COVID-19 during the shift from the hyper-inflammatory to the hypo-inflammatory phase." (PMID 32722596, 2020). "In conclusion, we found the concentration of sIL-2R is increasing in COVID-19 patients after illness onset and may be contribute to lymphopenia through IL-2 signaling inhibition." (PMID 32587367, 2020). "Similarly, severe COVID-19 patients have higher concentrations of IL-2, IL-6, IL-8 and TNF in the serum than mild cases, suggesting that the magnitude of cytokine storm is associated with the severity of the disease." (PMID 32698440, 2020). "The systemic inflammatory response observed in acute COVID-19, characterized by elevated levels of cytokines, such as IL-2, IL-10, IL-6, IL-8, C-Reactive Protein (CRP), and Tumor Necrosis Factor (TNF)-alpha, triggers acute phase reactions and, if sustained, may lead to end-organ damage." (PMID 40029921, 2025). "The SARS-CoV-2-specific polyfunctional Th1 CD4 T cell response (characterized by the co-expression of IFN-γ, TNF-α and/or IL-2), as seen in seropositive children, may be necessary for effective viral control and has been documented in COVID-19 convalescent adults." (PMID 38235336, 2024). "Th1 cells observed in individuals with COVID-19 demonstrated a distinctive expression of CXCR3 and CCR6, in addition to transcripts encoding cytokines and chemokines with anti-viral properties, such as CD154, IFN-γ, IL-2 (interleukin-2), and TNF (tumor necrosis factor)." (PMID 38675727, 2024).
COVID-19 (continued). "Thus, our findings indicate that IL-2 is essential in CRS in patients with severe COVID-19." (PMID 39359733, 2024). "Furthermore, there are SARS-CoV-2 cross-reactive and IL-2 secreted T cells in contacts of confirmed COVID-19 cases, which suggests that higher central memory T-cell counts might be positively associated with pre-existing SARS-CoV-2 cross-reactive T cells." (PMID 38842630, 2024). "Therefore, we speculate that spike protein may promote DCs to activate T cells to release a large amount of IL-2, leading to capillary leak syndrome in patients with severe COVID-19." (PMID 39359733, 2024). "Additionally, it was shown that COVID-19 patients had significant concentrations of IL-2 or IL-2R." (PMID 37742314, 2024). "First, we studied the profile of different soluble pro-inflammatory cytokines (GM-CSF, TNF-α, IFN-γ, IL-1β, IL-2, IL-6, IL-7, IL-10, IL-17A, IL-21) and chemokines mediating monocyte and neutrophil recruitment (IL8, CCL3), whose exacerbated production is associated with severe COVID-19." (PMID 36675231, 2023). "Furthermore, blood levels of T-cell-associated cytokines, mainly IFN-γ, TNF-α, IL-2, IL-6 and IL-17, increase during severe COVID-19, as opposed to measurements in controls." (PMID 37568402, 2023). "To date, there have been very few pilot studies investigating the use of low-dose IL-2 in COVID-19 patients, and these have been limited to the treatment of patients with acute disease, which may explain the reported lack of clear therapeutic benefit for these patients." (PMID 37700317, 2023). "Moreover, current mRNA-based COVID-19 vaccines are known to induce strong poly-specific T-cell responses mediated by IFN+ or IL-2+ CD8+ and CD4+ Th1-cells, which have been shown to present higher durability and cross-reactivity against CoV-2 variants than serum neutralizing antibody responses." (PMID 37449202, 2023). "We previously found a higher number of spike-specific IFNγ+, IL-2+, and polyfunctional IFNγ+/IL-2+ T-cells, with enhanced proliferative capacity, in aCD20-MS patients compared to a control group after primary vaccination series with two doses of mRNA-based COVID-19 vaccines." (PMID 37449202, 2023). "However, we remark that even when accounting for the later sampling time, community COVID-19 patients still displayed a slightly lower IL2-AIS score, which may indicate unknown cohort-specific confounding factors contributing to these differences." (PMID 37700317, 2023). "Furthermore, ARDS caused by COVID-19 differed from non-COVID-19 ARDS in that the former generated an increased expression of CCL5/RANTES while reducing IL-2, TNF-related apoptosis-inducing ligand (TRAIL), and granulocyte-colony-stimulating factor (G-CSF)." (PMID 36851766, 2023). "Finally, we compared the production of IL-2 in COVID-19-recovered subjects." (PMID 37111331, 2023). "Recent advances in the pathophysiologic understanding of coronavirus disease 2019 (COVID-19) suggests that cytokine release syndrome (CRS) has an association with the severity of disease, which is characterized by increased tumor necrosis factor α (TNF-α), interleukin (IL)-6, IL-2, IL-7, and IL-10." (PMID 35223745, 2022). "Interestingly, the second dose did not significantly further increase the production of IFN-ɣ or IL-2, suggesting that only one dose may be necessary to achieve protection mediated by cellular immunity in COVID-19 recovered HD patients." (PMID 35401504, 2022). "Moreover, levels of soluble IL-2R (CD25) were increased in severe COVID-19 patients, which could lead to binding of IL-2 with its receptor (IL-2R) and enhance apoptosis of Tregs." (PMID 35497875, 2022). "Dysregulation of T-cell mediated immunity is widely speculated to be the main cause of COVID-19 vaccine-induced MCD, with enhanced type 2 T-helper cell activity causing release of cytokines such as interferon-γ and IL-2 leading to increased permeability factor formation." (PMID 36291403, 2022).